UQCRC1 (ubiquinol-cytochrome c reductase core protein 1)
Description:
Component of the ubiquinol-cytochrome c oxidoreductase, a multisubunit transmembrane complex that is part of the mitochondrial electron transport chain which drives oxidative phosphorylation. The respiratory chain contains 3 multisubunit complexes succinate dehydrogenase (complex II, CII), ubiquinol-cytochrome c oxidoreductase (cytochrome b-c1 complex, complex III, CIII) and cytochrome c oxidase (complex IV, CIV), that cooperate to transfer electrons derived from NADH and succinate to molecular oxygen, creating an electrochemical gradient over the inner membrane that drives transmembrane transport and the ATP synthase. The cytochrome b-c1 complex catalyzes electron transfer from ubiquinol to cytochrome c, linking this redox reaction to translocation of protons across the mitochondrial inner membrane, with protons being carried across the membrane as hydrogens on the quinol. In the process called Q cycle, 2 protons are consumed from the matrix, 4 protons are released into the intermembrane space and 2 electrons are passed to cytochrome c (By similarity). The 2 core subunits UQCRC1/QCR1 and UQCRC2/QCR2 are homologous to the 2 mitochondrial-processing peptidase (MPP) subunits beta-MPP and alpha-MPP respectively, and they seem to have preserved their MPP processing properties (By similarity). May be involved in the in situ processing of UQCRFS1 into the mature Rieske protein and its mitochondrial targeting sequence (MTS)/subunit 9 when incorporated into complex III (Probable). Seems to play an important role in the maintenance of proper mitochondrial function in nigral dopaminergic neurons.
Synonyms: D3S3191; QCR1; UQCR1; PKNPY
Tractability: Small molecule: a structure with a bound ligand is known. Antibody: UniProt places it where antibodies can reach, with medium confidence. PROTAC: ubiquitination databases record sites on it; its protein half-life has been measured.
Gene: Protein-coding gene on chromosome 3 (48,599,002 to 48,610,976, reverse strand). Ensembl gene ENSG00000010256.
Subcellular location: Mitochondrion inner membrane
Subcellular location (Human Protein Atlas): Mitochondria
Pathways (Reactome):
Metabolism: Complex III assembly; Respiratory electron transport
Gene Ontology:
Molecular function: protein binding; ubiquitin protein ligase binding; quinol-cytochrome-c reductase activity; metal ion binding; protein-containing complex binding
Biological process: aerobic respiration; cellular respiration; mitochondrial electron transport, ubiquinol to cytochrome c; oxidative phosphorylation; proton transmembrane transport; response to activity; response to alkaloid
Cellular component: mitochondrial inner membrane; mitochondrion; respiratory chain complex III; mitochondrial processing peptidase complex; respiratory chain complex; membrane
Genetic constraint (gnomAD): Loss-of-function variants: 34 observed, 59.36 expected, observed/expected ratio (o/e) 0.57, 90% interval 0.44 to 0.76. The upper end of that interval is the gene's LOEUF score, 0.76, which puts it in group 3 of 6, group 1 being the genes least tolerant of losing a copy. Missense variants: 610 observed, 658.98 expected, observed/expected ratio (o/e) 0.93, 90% interval 0.87 to 0.99. Synonymous variants: 276 observed, 260.2 expected, observed/expected ratio (o/e) 1.06, 90% interval 0.96 to 1.17.
Gene-disease validity (ClinGen):
ClinGen rates the evidence that UQCRC1 causes each of these diseases.
mitochondrial disease (autosomal dominant): Disputed.
Homologues: Orthologues: chimpanzee UQCRC1 (100% identical), macaque UQCRC1 (94% identical), dog UQCRC1 (91% identical), rabbit UQCRC1 (90% identical), guinea pig UQCRC1 (89% identical), mouse Uqcrc1 (89% identical), pig UQCRC1 (89% identical), rat Uqcrc1 (88% identical), tropical clawed frog uqcrc1 (65% identical), zebrafish uqcrc1 (61% identical), Caenorhabditis elegans C05D11.1 (21% identical), Caenorhabditis elegans ucr-2.2 (18% identical). Paralogues in human: PMPCB (56% identical), PMPCA (30% identical), NRDC (22% identical), PITRM1 (20% identical), UQCRC2 (20% identical), IDE (20% identical).
Diseases named in the same sentence as UQCRC1 in open-access papers:
UQCRC1 is named in the same sentence as 57 diseases in open-access papers, as found by Europe PMC text mining. Sharing a sentence is not in itself a finding about the gene and the disease. The quoted sentences say what the papers report.
Parkinson disease (11 papers, 2011 to 2025). A progressive degenerative disorder of the central nervous system characterized by loss of dopamine producing neurons in the substantia nigra and the presence of Lewy bodies in the substantia nigra and locus coeruleus. "Mitochondrial ubiquinol-cytochrome c reductase core protein 1 (UQCRC1)-associated parkinsonism with polyneuropathy is a rare genetic disorder that is caused by a missense mutation, c.941A > C (p.Tyr314Ser) in the UQCRC1 gene." (PMID 38666843, 2024). "UQCRC1 deregulation has been reported to be involved in a variety of disorders, such as Parkinson's disease and pancreatic cancer." (PMID 40022141, 2025). "Taken together, these observations show that taurine has certain beneficial effects on Alzheimer’s disease, Parkinson’s disease, and dementia, and our data links this amino acid to the mitochondrial enzyme UQCRC1." (PMID 36771351, 2023). "This study investigated the pathogenicity of UQCRC1 in a Taiwanese cohort of patients with Parkinson's disease (PD)." (PMID 36570444, 2022). "Of special interest was the classification of “KEGG routes”, where the proteins ATP5A1, ATP5B, NDUFS1, and UQCRC1 participate in both oxidative phosphorylation and diseases such as Parkinson’s, Alzheimer’s, and Huntington’s." (PMID 30678170, 2019). "Second, and more interesting, the oxidative phosphorylation chain, including seven genes (ATP5C1, ATP6AP1, ATP6V1H, COX5B, COX6B1, NDUFA1, and UQCRC1), five of them shared with Huntington's and Parkinson's disease KEGG categories." (PMID 21541025, 2011). "Furthermore, numerous genes have recently been implicated in Parkinson’s disease, such as CHCHD2, LRP10, TMEM230, UQCRC1, and VPS13C." (PMID 35328025, 2022).
osteosarcoma (7 papers, 2016 to 2022). A usually aggressive malignant bone-forming mesenchymal neoplasm, predominantly affecting adolescents and young adults. "UQCRC1 is upregulated in breast cancer, ovarian cancer, and PC, while downregulated in colorectal cancer, osteosarcoma, and clear cell renal cell carcinoma." (PMID 35769718, 2022). "In contrast, osteosarcoma cell proliferation can be enhanced via targeting of ubiquinol-cytochrome c reductase core protein 1 (UQCRC1) with miR-214-3p." (PMID 35887244, 2022). "UQCRC1 was demonstrated to be highly expressed in breast and ovarian tumors as well as in osteosarcoma cells and tissues." (PMID 28676853, 2017). "Former studies reported deregulation of these genes in cancer: UQCRC1 expression levels were increased in osteosarcoma, breast and ovarian tumors." (PMID 27845902, 2016). "The expression of UQCRC1 is increased in osteosarcoma cells." (PMID 27941907, 2016). "The authors found that 8 proteins, including HSP70, UQCRC1, and PRDX4, were increased in osteosarcoma and therefore may be potential molecular targets for osteosarcoma diagnosis and therapy." (PMID 28387323, 2017).
Alzheimer disease (6 papers, 2020 to 2025). A progressive, neurodegenerative disease characterized by loss of function and death of nerve cells in several areas of the brain leading to loss of cognitive function such as memory and language. "The dysregulated expression of UQCRC1 in the blood and skeletal muscle has been associated with Alzheimer’s disease." (PMID 36771351, 2023). "Ubiquinol-cytochrome C reductase core protein I (UQCRC1), a mitochondrial protein, is known as a biomarker of Alzheimer’s disease and is located in complex III in the respiratory chain." (PMID 38914933, 2024). "UQCRC1 acts on cytochrome C upstream or internally of mitochondrial electron transport and has been studied extensively in Alzheimer's disease, which may play an important role in the targeted therapy of pancreatic cancer." (PMID 36404333, 2022).
ovarian carcinoma (6 papers, 2015 to 2025). A malignant neoplasm originating from the surface ovarian epithelium. "Furthermore, in both breast and ovarian carcinomas, UQCRC1 expression is positively correlated with mtDNA-encoded COX2 expression." (PMID 26067091, 2015). "To understand how TRPM7 modulated metabolic reprogramming in ovarian cancer, we analyzed the expression of TRPM7, glycolysis-related HK2, PDK1, and OXPHOS-related IDH3B and UQCRC1 in 60 ovarian cancer tissues by IHC." (PMID 35101076, 2022). "Furthermore, TRPM7 silencing also decreased the relative levels of glycolysis-related HK2 and PDK1 expression as well as PKM2 nuclear translocation, but increased OXPHOS-related IDH3B and UQCRC1 expression in ovarian cancer cells and tissues." (PMID 35101076, 2022). "The impacts of TRPM7 silencing on the levels of glycolysis-related HK2, PDK1 and oxidative phosphorylation (OXPHOS)-related IDH3B and UQCRC1, HIF-1α expression and AMPK phosphorylation were determined in ovarian cancer." (PMID 35101076, 2022). "In parallel, TRPM7 silencing decreased the glucose uptake of tumor-bearing mice and TRPM7 levels were negatively correlated with IDH3B and UQCRC1, but positively with HK2 and PDK1 expression in ovarian cancer tissues." (PMID 35101076, 2022). "Oncoprint profile of CYCS, VEGFA, IL6, UQCRC1, UQCRFS1, COX5B, ACKR3/CXCR7, and FYN indicated that these genes were either amplified or overexpressed in 4–25% of the ovarian cancer patients." (PMID 34439877, 2021). "The identification of CYCS, VEGFA, IL6, UQCRC1, UQCRFS1, COX5B, ACKR3/CXCR7, and FYN as pro-tumorigenic nodes designates them as the novel and potentially druggable targets for effective targeted adjuvant therapy for ovarian cancer." (PMID 34439877, 2021).
pancreatic cancer (5 papers, 2020 to 2025). "UQCRC1 encodes the mitochondrial ubiquinol-cytochrome c reductase core protein I, which is part of Complex I of the mitochondrial respiratory chain and was shown to be critically involved in the oncogenic reprogramming of metabolic pathways in pancreatic cancer." (PMID 34439877, 2021).
ovarian tumors (4 papers, 2016 to 2017). "The UQCRC1 was highly expressed in breast and ovarian tumors, and played a potential role in tumorigenesis." (PMID 28860661, 2017).
polyneuropathy (4 papers, 2022 to 2024). A disease or disorder affecting more than one nerve. "A recent Taiwanese study reported variants of the ubiquinol-cytochrome c reductase core protein 1 (UQCRC1) gene linked to autosomal dominant parkinsonism with polyneuropathy." (PMID 36570444, 2022). "Interestingly, mutations in the mitochondrial Ubiquinol-Cytochrome C Reductase Core Protein 1 (UQCRC1) gene have been found recently to cause autosomal dominant parkinsonism with polyneuropathy, characterized molecularly by mitochondrial complex III dysfunction." (PMID 35513611, 2022). "Third, electrophysiologic data were not available for assessing polyneuropathy among the participants with UQCRC1 variants." (PMID 36570444, 2022).
colorectal cancer (3 papers, 2020 to 2024). A primary or metastatic malignant neoplasm that affects the colon or rectum. "Our result is similar to previous studies showing the reduced gene expression of Uqcrc1 in UC and colorectal cancer." (PMID 38668322, 2024).
esophageal squamous cell carcinoma (3 papers, 2016 to 2025). Esophageal squamous cell carcinoma (ESCC) is a type of esophageal carcinoma (EC) that can affect any part of the esophagus, but is usually located in the upper or middle third. "Using mass spectrometry, UQCRC1 was identified as one of the three up regulated proteins in the serum from patients with esophageal squamous cell carcinoma and the results suggested that UQCRC1 might be a useful serological marker for this type of cancer." (PMID 27941907, 2016).
melanoma (3 papers, 2013 to 2023). A malignant, usually aggressive tumor composed of atypical, neoplastic melanocytes. "We found that changes in some crucial proteins, such as Hsp60, HspB1, prohibitin, IDH, and UQCRC1, were associated with apoptosis or the mitochondrial function against melanoma cells." (PMID 23880933, 2013). "In addition, some anticancer treatments, for example, treatment of CAL-27 cells with 11-dehydrosinulariolide and A375 melanoma cells with sinulariolide, markedly downregulate UQCRC1." (PMID 28676853, 2017). "Several cytosolic (PGM2, LDHA and pPKM2) and mitochondrial (UQCRC1, COX4 and ATP5B) enzymes are downregulated by HPF treatment, suggesting a generalized reduction of vital functions in melanoma cells." (PMID 36674794, 2023).
Obesity (3 papers, 2011 to 2023). Accumulation of substantial excess body fat. "Our data showed that ATP synthase D chain, ubiquinol cytochrome-C reductase core protein 1 and electron transfer flavoprotein subunit alpha peptide levels were altered with obesity." (PMID 20859605, 2011). "High expression of UQCRC1 leads to mitochondrial dysfunction and reduced ATP utilization, thereby accelerating the process of lipid deposition and insulin resistance in skeletal muscle, ultimately leading to the development of type 2 diabetes and obesity." (PMID 36782329, 2023). "UQCRC1 expression was also found to be reduced in visceral adipose tissues from obesity-prone mice." (PMID 26121299, 2015).
sleep disorder (3 papers, 2022 to 2025). A change from the patient's baseline sleeping pattern, in the hours slept and/or an alteration/dysfunction in the stages of sleep. "ATP5B, COX5A, GAPDH NDUFV2, SOD1, UQCRC1, and UQCRC2 have been reported as sleep deprivation and sleep disorder-related genes, and these studies have contributed to the development of candidate biomarkers for the diagnosis and treatment of plateau-induced sleep disorders." (PMID 36860517, 2023).
gastric cancer (2 papers, 2016 to 2020). A primary or metastatic malignant neoplasm involving the stomach. "In conclusion, our study revealed the role of ANXA1, NNMT, Fibulin-5 and UQCRC1 in gastric cancer progression." (PMID 27941907, 2016).
pancreatic ductal adenocarcinoma (2 papers, 2021 to 2022). An infiltrating adenocarcinoma that arises from the epithelial cells of the pancreas. "UQCRC1 has a carcinogenic effect in pancreatic ductal adenocarcinoma (PDAC) and can be used as a potential prognostic marker and therapeutic target for PDAC." (PMID 36404333, 2022). "UQCRC1 is overexpressed in pancreatic ductal adenocarcinomas, osteosarcomas, as well as in breast and ovarian cancer, while it is downregulated in the clear cell subtype of renal cell carcinomas, CRC, gastric, and breast cancer." (PMID 34361072, 2021). "The overexpression of UQCRC1 increased the growth rates of pancreatic ductal adenocarcinoma cells in vitro and in vivo through activating the eATP/P2Y2-RKT/AKT pathway." (PMID 34361072, 2021).
brain ischemia (1 paper, 2021). Diminished or absent blood supply to the brain caused by obstruction (thrombosis or embolism) of an artery resulting in neurologic damage. "Deficiency in UQCRC1 worsens neurological outcomes after brain ischemia or hypoxia." (PMID 34884479, 2021).
colitis (1 paper, 2024). Inflammation of the colon. "In our study, we observed a significant reduction in UQCRC1 in colitis, which is a subunit of mitochondrial complex III in ETC." (PMID 38668322, 2024).
emphysema (1 paper, 2022). "We found significantly higher UQCRC1 levels in areas with severe emphysema compared to mild." (PMID 35884802, 2022).
encephalomyopathy (1 paper, 2024). "On the other hand, the consistent finding of extensively interconnected mitochondrial networks observed in UQCRC1-mutant cells is also found in UQCRC2-mutant fibroblasts derived from patients with severe encephalomyopathy." (PMID 38666843, 2024).
endothelial dysfunction (1 paper, 2023). In vascular diseases, endothelial dysfunction is a systemic pathological state of the endothelium (the inner lining of blood vessels) and can be broadly defined as an imbalance between vasodilating and vasoconstricting substances produced by (or acting on) the endothelium. "Endothelial dysfunction was observed in PA-treated HAECs, including impaired total antioxidant capacity, cell viability, NO levels, and eNOS, MFN2 and UQCRC1 protein levels, as well as significant up-regulation of IL6, MMP1, and CHOP mRNA levels." (PMID 37237885, 2023). "In addition, co-treatment with PA and NAC reduced endothelial dysfunction, including restoration of total antioxidant capacity, cell viability, NO levels, and eNOS, DRP1, MFN2, NDUFS3, and UQCRC1 protein levels, as well as inhibition of IL6 and CHOP mRNA levels." (PMID 37237885, 2023).
gastric adenocarcinoma (1 paper, 2016). "Nonetheless, Cai’s findings on UQCRC1 down regulation in gastric cardia cancer samples are consistent with our results in gastric adenocarcinoma." (PMID 27941907, 2016).
hepatocellular carcinoma (1 paper, 2017). A malignant tumor that arises from hepatocytes. "UQCRC1 was found to be increased in tumor tissues and might contribute to the development of hepatocellular carcinomas tumors." (PMID 28750029, 2017).
ischemia (1 paper, 2017). A hypoperfusion of the BLOOD through an organ or tissue caused by a PATHOLOGIC CONSTRICTION or obstruction of its BLOOD VESSELS, or an absence of BLOOD CIRCULATION. "In conclusion, the overexpression of UQCRC1 can protect H9c2 cardiac cells against simulated ischemia/reperfusion, and this cardio-protective effect is likely mediated by zinc binding." (PMID 28676853, 2017).
kidney transplant (1 paper, 2021). A surgical procedure in which one or both kidneys from a donor are implanted into a recipient. "Interestingly, dysregulation of UQCRC1 has been implicated in kidney transplant rejection." (PMID 34884479, 2021).
lung adenocarcinoma (1 paper, 2022). A carcinoma that arises from the lung and is characterized by the presence of malignant glandular epithelial cells. "Among those proteins, UQCRC1 had an area under the curve of 0.960, and 5 proteins had an area under the curve from 0.90 to 0.95, suggesting that these hub proteins might have discriminatory potential in lung adenocarcinoma, P < 0.05." (PMID 36404333, 2022).
lymph node metastasis (1 paper, 2020). "Downregulation of UQCRC1 has been correlated to lymph node metastasis and a poor prognosis of CRC." (PMID 32793472, 2020).
myocarditis (1 paper, 2019). Myocarditis is a condition that is characterized by inflammation of the heart muscle (myocardium). "Cytochrome c reductase complex III, including UQCRQ, UQCRC1, UQCRC2, are oxidatively damaged in response to infection in chagasic myocarditis hearts." (PMID 31275164, 2019).
neuroblastoma (1 paper, 2025). Neuroblastoma (NB) is the most common solid, extracranial childhood tumor. "Similarly, in UQCRC1-mutant neuroblastoma cells, mitochondrial respiration—including basal respiration (BR), ATP production linked to electron transport, and CIII-dependent respiration—was markedly impaired in the sham group relative to WT." (PMID 40801581, 2025).
oncocytoma (1 paper, 2016). "In contrast, UQCRC1 expression was distinctly lower in pRCC (1.63; p<0.001), chRCC (2.70; p<0.001) and oncocytoma (2.80; p<0.001)." (PMID 27845902, 2016).
psoriasis (1 paper, 2021). An autoimmune condition characterized by red, well-delineated plaques with silvery scales that are usually on the extensor surfaces and scalp. "In blood heat syndrome, a common syndrome of psoriasis, we found that a large number of oxidative phosphorylation pathway-related genes, such as NDUFS8, NDUFA6, and UQCRC1, showed syndrome-specific expression abnormalities." (PMID 35126107, 2021).